AHR (aryl hydrocarbon receptor)
Diseases named in the same sentence as AHR in open-access papers (continued):
Sharing a sentence is not in itself a finding about the gene and the disease.
ovarian carcinoma (31 papers, 2014 to 2026). A malignant neoplasm originating from the surface ovarian epithelium. "Therefore, in our study, we examined the role and involvement of AhR in OC progression and chemoresistance and the underlying mechanisms of AhR in the pathogenesis of ovarian cancer." (PMID 35742838, 2022). "Moreover, nuclear localization of AhR has been associated with a worse outcome for patients with high-grade anaplastic meningioma or ovarian cancer." (PMID 33451095, 2021). "Consequently, low cytoplasmic AhR expression seems to be associated with improved survival in ovarian cancer patients." (PMID 31212758, 2019). "CircPAFAH1B2 and circUBAP2 bind to IGFBP2 and stabilize dickkopf 3(DKK3) and aryl hydrocarbon receptor (AHR) mRNAs to promote the peritoneal dissemination of ovarian cancer." (PMID 40710359, 2025). "IDO1 is also reported to promote PD-L1 expression in ovarian cancer cells in an AhR-dependent manner." (PMID 38451784, 2024). "In the current study, we compared proliferation following the genetic knockdown of IDO1, TDO2, and AhR in ovarian cancer cell lines and observed a more robust antiproliferation response in the setting of TDO2 knockdown." (PMID 38451784, 2024). "In human ovarian cancer tissues, immunohistochemistry analysis has shown positive AhR staining in a range of histological subtypes." (PMID 38807762, 2024). "AHRR, a protein that negatively controls AHR-expressed genes by competing with AHR to bind to heterobetaine-responsive elements is downregulated in several tumor types, including colon, breast, gastric, cervical, and ovarian cancers." (PMID 39201782, 2024). "IDO1 is also expressed by ovarian carcinomas where its levels are sustained by an autocrine AhR-IL-6-STAT3 signaling loop." (PMID 38807762, 2024). "TCDD-activated AhR also promotes EMT in ovarian cancer cells, and the current study demonstrated that both ligand-activated AhR promote EMT." (PMID 38434684, 2024). "To investigate the relative contributions of IDO1 versus TDO2, we generated shRNA-mediated knockdown IDO1 and TDO2, as well as the downstream KYN receptor AhR in human ovarian cancer OVCAR3 cells." (PMID 38451784, 2024). "Since active IL4I1 is sufficiently expressed in ovarian cancer patients to modulate ascitic PP and 4HPP levels, this would likely allow the enhanced production of Trp-derived AhR agonists by IL4I1." (PMID 36765849, 2023). "Recently, it has been demonstrated that AF inhibits HIF1α expression in an AhR-independent fashion in certain breast, renal and ovarian cancer cell lines." (PMID 32443455, 2020). "As a ligand-activated transcription factor of the carcinogen TCDD, the aryl hydrocarbon receptor (AhR) was identified as a potential oncogenic factor influencing ovarian cancer biology and outcome." (PMID 31212758, 2019). "Out of 148 successfully stained ovarian cancer specimens, 145 (98%) showed positive nuclear AhR expression." (PMID 31212758, 2019). "In our study, we examined the expression of the aryl hydrocarbon receptor in different histological types of ovarian cancer (serous, clear cell, endometrioid, and mucinous) and its association with clinicopathological data and overall survival." (PMID 31212758, 2019). "In our study, we found that ovarian cancer patients with high cytoplasmic AhR expression have different survival outcomes depending on their FSHR levels." (PMID 31212758, 2019). "So far, only little is known about the specific role of AhR in ovarian cancer, and this study represents the first investigation focusing on AhR expression in different histological subtypes and its impact on survival." (PMID 31212758, 2019). "By immunohistochemistry, AhR staining was analyzed in a subset of 156 samples of ovarian cancer patients." (PMID 31212758, 2019).
ovarian carcinoma (continued). "Ovarian cancer patients with high cytoplasmic AhR and concurrent FSHR expression had the worst outcome (median 69.72 vs. 43.32 months; p = 0.043)." (PMID 31212758, 2019). "The elevated expression of AhR in poorly differentiated ovarian cancer is concordant with its activity of inducing the transcription of several enzymes which are crucial for the activation of carcinogens (e.g., polycyclic aromatic hydrocarbons)." (PMID 31212758, 2019). "Other studies have linked STAT3 and the aryl hydrocarbon receptor (AHR) to IDO expression in human NSCLC and ovarian cancer." (PMID 27148255, 2016). "This is also part of the AhR–ER interplay in estrogen-positive and -negative cancers, as seen, for example, in breast and ovarian cancers, and overall low AhR expression is associated with reduced cancer risk." (PMID 40650089, 2025). "However, treatment of ovarian cancer cell lines with AhR agonists appears to have varying effects depending on the ligand and cell type." (PMID 38807762, 2024). "Further investigation is needed to clarify the tumorigenic role of AhR in ovarian cancers." (PMID 38807762, 2024). "We found that AHR expression was greater in human and chicken ovarian cancer." (PMID 31923221, 2020). "AHR, a potential inflammasomes regulator, was similarly higher in hen and human ovarian cancer." (PMID 31923221, 2020). "Ovarian cancer patients with high levels of AhR and FSHR could potentially benefit from treatment with gonadotropin-releasing hormone (GnRH) agonists/antagonists." (PMID 31212758, 2019). "Thus, further studies are needed to understand the mechanisms and effects of AhR pathways by focusing specifically on ovarian cancer and its different histological subtypes." (PMID 31212758, 2019). "This potential anti-ovarian cancer activity of AhR could help optimize strategies for ovarian cancer therapy." (PMID 27243009, 2016). "Notably, the expression of AhR has been shown to mediate the IL-6 expression in ovarian cancer, and Kyn derived from Trp metabolism could efficiently promote the activation of AhR signals in a diverse of tumor cells." (PMID 34657635, 2021). "In ovarian cancer, ITE has been observed to regulate cancer cell proliferation and migration via AhR, suggesting its potential for optimizing ovarian cancer therapy." (PMID 39211042, 2024). "5F203 induced enhanced CYP1A1 expression; AhR translocation and reactive species formation (ROS) in IGROV-1 cells and ascites-isolated ovarian cancer cells that were sensitive to 5F203." (PMID 32443455, 2020). "AHR and AHRR were assessed to determine if the expression correlated with the inflammasome in ovarian cancer." (PMID 31923221, 2020). "Our data suggest that AhR and FSHR levels correlate with each other, and their concurrent expression was observed in ovarian cancer patients with the worst outcome." (PMID 31212758, 2019). "We aimed to elucidate the prognostic impact of AhR, its correlation with the follicle-stimulating hormone receptor (FSHR), and their functional role in ovarian cancer." (PMID 31212758, 2019). "In a variation on this theme, but also involving AhR, a positive feedback loop encompassing IL-6 expression and STAT3 has recently been described in various tumor cells, including ovarian cancer." (PMID 26343197, 2015). "For instance, AhR knockdown in HepG2 cells was shown to decrease cell proliferation due to downregulation of cell-cycle-related genes, whereas agonism of AhR by TCDD was shown to suppress cell proliferation of OVCAR-3, a human ovarian cancer cell line." (PMID 33615198, 2021). "In human ovarian cancer, there is one report that AHR mRNA was not changed in primary tissue, while another study found that AHR expression was elevated in ovarian cancer cell lines." (PMID 31923221, 2020). "However, the examination of both AhR and FSHR revealed that AhR staining intensity is strongly correlated with FSHR expression in the ovarian cancer specimens." (PMID 31212758, 2019).
ovarian carcinoma (continued). "Furthermore, our study revealed a strong correlation between (cytoplasmic) AhR and FSHR in ovarian cancer patients." (PMID 31212758, 2019). "Due to the scarce amount of knowledge on AhR and its interaction with FSHR in ovarian cancer, an evaluation of AhR expression in different histological subtypes and of its correlation and impact on cancer biology and survival was the primary aim in the current study." (PMID 31212758, 2019). "Moreover, in ovarian cancer, it has been demonstrated that ITE regulates cancer cell proliferation and migration via AhR using in vitro and/or in vivo models." (PMID 27243009, 2016). "Importantly, GA-NPs@DCV exerts potent anti-ovarian cancer effects by promoting immune activation, inhibiting immune evasion through the Stat3/IDO1/AhR signaling axis, and remodeling tumor immune microenvironment via regulation of the tryptophan metabolic pathway." (PMID 41743162, 2026). "Interestingly, our previous study showed that DMU-212 suppressed the AhR protein expression in the nuclear fraction of ovarian cancer A-2780 cells and their non-cancerous counterparts." (PMID 37572199, 2023). "In contrast, 5F203 failed to induce CYP1A1 expression, AhR translocation or oxidative stress in 5F203-resistant SKOV-3 cells, or in ovarian cancer ascites cells inherently resistant to this agent." (PMID 32443455, 2020).
ulcerative colitis (31 papers, 2018 to 2026). An inflammatory bowel disease involving the mucosal surface of the large intestine and rectum. "DNA methylation alterations at the loci cg14647125 and cg23916896 (both located in the AHR repressor gene body) are linked to ulcerative colitis risk (P = 0.001 and 0.002, respectively)." (PMID 40765830, 2025). "A recent study linking microbial metabolites implicated in the disease course of paediatric ulcerative colitis indicated that a decrease in tryptophan metabolites, many of which activate the AHR, is associated with moderate to severe ulcerative colitis." (PMID 39242971, 2024). "In a DSS-induced mouse organoid inflammation model, Hymenolepis nana antigens promote intestinal stem cell proliferation and differentiation through the AhR/IL-22 signaling pathway, thereby alleviating ulcerative colitis." (PMID 41019044, 2025). "AHR expression was positively correlated with ODC1 in intestinal mucosal biopsies from patients with ulcerative colitis." (PMID 39113799, 2024). "In humans, reduced fecal concentrations of indole derivatives in ulcerative colitis (UC) patients compared to healthy volunteers were accompanied by a trend towards reduced fecal AhR activity." (PMID 36894983, 2023). "Baicalein strengthens the intestinal epithelial barrier through the AHR/IL-22 pathway in ILC3s, thereby reducing the symptoms of ulcerative colitis." (PMID 37179416, 2023). "As one of the ligands of aryl hydrocarbon receptor (AhR), baicalein, isolated from Scutellaria baicalensis Georgi, has been proved to exert potential therapeutic effects on ulcerative colitis (UC), but its therapeutic mechanism remains obscure." (PMID 33082710, 2020). "Authentically, ulcerative colitis can be alleviated by regulating the differentiation of naïve CD4+ T cells via AhR activation." (PMID 33082710, 2020). "Thus, we propose a potential novel therapeutic strategy by elucidating how HQD promotes epithelial regeneration and repair by influencing the gut microbiota-tryptophan-AhR-ISC axis in ulcerative colitis." (PMID 41530817, 2026). "Therapeutic interventions targeting the AhR/IL-22 axis may offer novel avenues for the management of ulcerative colitis, potentially enhancing autophagic processes and improving intestinal health outcomes." (PMID 41019044, 2025). "An important study was undertaken to examine whether the aryl hydrocarbon receptor (AhR) mediated quercetin’s intestinal barrier repair potential to ameliorate ulcerative colitis." (PMID 39858545, 2025). "For example, miR167a from Z. officinale-PDEVs may activate the aryl hydrocarbon receptor (AHR) signaling pathway to alleviate ulcerative colitis by promoting IL-22 expression." (PMID 38108066, 2023). "Although not the main focus of this article, it is intriguing that indigo naturalis, through the aryl hydrocarbon receptor (AhR), was able to stimulate the protective IL-22 and resulted in mucosal healing in a randomized, controlled trial in patients with ulcerative colitis." (PMID 31125257, 2019). "Clinical observations in patients with ulcerative colitis revealed impaired IPA-AhR signaling, evidenced by a 42% reduction in mucosal AhR expression and decreased fecal IPA levels (2.1 μM vs. 5.8 μM in healthy controls)." (PMID 40825672, 2025). "Simultaneously, it enhances the integrity of the intestinal epithelial barrier via the AhR/IL-22 pathway in ILC3, thereby ameliorating ulcerative colitis." (PMID 38962743, 2024). "Likewise, indole-3-carbinol attenuated necroptosis and inflammation in intestinal epithelial cells (IECs) by activating aryl hydrocarbon receptor (AHR), which played a protective role in a mouse model of DSS-induced ulcerative colitis." (PMID 40730483, 2025). "Norisoboldine (NOR), a natural aryl hydrocarbon receptor (AhR) agonist, has been demonstrated to attenuate ulcerative colitis (UC) and induce the generation of Treg cells." (PMID 29449535, 2018).
inflammatory skin disease (30 papers, 2014 to 2026). Inflammatory skin disorders covers a broad category that includes many conditions ranging in severity, from mild itching to grave medical health complications These disorders are common in people of all ages and races. "Dysregulation of AHR signaling has been implicated in inflammatory skin diseases including AD and targeting AHR signaling has been proposed as a potential treatment option." (PMID 41403940, 2025). "PM2.5 readily penetrates the skin via the aryl hydrocarbon receptor, causing skin senescence, inflammatory skin diseases, DNA damage, and carcinogenesis." (PMID 34573124, 2021). "Following on from this finding, AHR modulators have been investigated as potential therapeutics for inflammatory skin diseases." (PMID 40004095, 2025). "Since AhR activation is associated with the regulation of inflammatory and immunological processes in the skin, AhR agonists thus provide a promising therapeutic strategy for the treatment of inflammatory skin diseases." (PMID 40574044, 2025). "The successful development of AhR-targeting medications like tapinarof further validates AhR as an important therapeutic target for inflammatory skin disorders—tapinarof has been shown to reduce itching in humans." (PMID 40723482, 2025). "The NRF2 pathway is significantly intertwined with that of AHR, and further studies must reconcile both as we resolve the dynamic relationship between AHR and inflammatory skin disease." (PMID 38344408, 2024). "AHR contributes to the pathogenesis of these inflammatory skin diseases by regulating the production of inflammatory cytokines such as TNF-α and IL-8 and the Th17 cytokine network." (PMID 37834081, 2023). "For instance, current findings advise that the aryl hydrocarbon receptor (AHR)/AHR-nuclear translocator (ARNT) axis possesses therapeutic implications for treating inflammatory skin disease issues, providing more evidence of the critical function of filaggrin." (PMID 37372008, 2023). "Due to the expression of AHR in various cells, this receptor represents a promising target for therapy for inflammatory skin disorders." (PMID 37511138, 2023). "It is apparent that short chain fatty acid and aryl hydrocarbon receptor signaling pathways are essential to many metabolic and immune processes affected by inflammatory skin diseases." (PMID 37623895, 2023). "On the other hand, targeting AhR/Nrf2 is emerging as a novel treatment option for air pollutants that induce or exacerbate inflammatory skin diseases." (PMID 37445680, 2023). "Constitutive AhR activation has been shown to be related to inflammatory skin disease after exposure to occupational or environmental xenobiotics." (PMID 35458697, 2022). "AhR has effects of inflammatory skin diseases, but there is still a long way to go before its practical against inflammatory diseases." (PMID 35625824, 2022). "Many studies evaluate how the dysregulation of the AhR signaling pathway can be involved in the pathogenesis of inflammatory skin diseases and tumors and, consequently, these aspects make AhR particularly interesting as a possible therapeutic target." (PMID 34299118, 2021). "Some studies demonstrated that AhR antagonists can prevent skin cancer, whereas the agonists can be useful for the treatment of inflammatory skin diseases." (PMID 34299118, 2021). "For example, this inhibitory effect has been employed to modulate the AHR axis in cancer research to reverse disease progression, in immunology to evaluate AHR signaling in inflammatory skin diseases, and in toxicology to characterize the effects of fungicide exposure in human placental cells." (PMID 41596714, 2026). "Young AHR-KO mice subjected to mechanical stress display elevated trans-epidermal water loss (TEWL), a biomarker of skin barrier integrity, which is increased when the barrier is compromised, such as in inflammatory skin disease." (PMID 40004095, 2025).
inflammatory skin disease (continued). "Therefore, certain AHR agonists are called therapeutic AHR-modulating agents (TAMAs), and are recognized as promising treatments for inflammatory skin diseases." (PMID 36362566, 2022). "Research on AhR often leads to contradictory interpretations of inflammatory skin diseases." (PMID 35625824, 2022). "Several studies have shown that blocking AhR signaling prevents or treats skin cancer, whereas activating AhR could be beneficial in inflammatory skin diseases." (PMID 33151407, 2021). "We did not detect a change in the skin TEWL, nor an increase in cutaneous inflammation, indicating that systemic ligand activation of the murine AHR via in utero and lactational exposure does not cause an inflammatory skin disease as found in the AHR-CA mice." (PMID 34437510, 2021). "Moreover, we discuss the role of AhR in skin pathological processes, including inflammatory skin diseases, pigmentation disorders and cancer." (PMID 33499346, 2021). "Modulating the AhR and nuclear factor-erythroid 2-related factor 2 (NRF2) pathways is emerging as a novel approach in treating AD and other inflammatory skin diseases." (PMID 39722037, 2024). "Hence, it is important to study new AhR activators able to mimic the beneficial anti-inflammatory and pro-differentiative effects, which are exerted physiologically by natural ligands, considering AhR as a valid target for therapeutic approaches in inflammatory skin diseases." (PMID 34299118, 2021).